STAT3 (signal transducer and activator of transcription 3)
Diseases named in the same sentence as STAT3 in open-access papers (continued):
Sharing a sentence is not in itself a finding about the gene and the disease.
sarcoidosis (12 papers, 2014 to 2025). Sarcoidosis is a multisystemic disorder of unknown cause characterized by the formation of immune granulomas in involved organs. "STAT1 and STAT3 play a role in type 1 T-helper (Th1) and Th17 cell differentiation and are implicated in the pathogenesis of sarcoidosis." (PMID 37628972, 2023). "It has also been shown that pharmacologic inhibition of STAT3 via upstream Janus kinase (JAK) inhibition leads to complete resolution of skin lesions in sarcoidosis patients." (PMID 32849608, 2020). "This pathway may be correlated with PD-1 manipulation of STAT3 expression in patients with sarcoidosis since a recent study showed that PD- 1 inhibits PI3K expression in CD4+ T cells in sarcoidosis." (PMID 36544757, 2022). "Interestingly, 79 gene transcripts were upregulated both in sarcoidosis monocytes and macrophages, and these genes were enriched in “Interferon gamma” and “STAT3 Signaling” pathways, with the inclusion of both STAT3 and JAK3 gene transcripts." (PMID 38353578, 2024). "Importantly, MIA-602, also reduced inflammation and fibrosis in a mouse model of lung injury, by inhibiting inflammatory pathways, such as signal transducer and activator of transcription 3 (STAT3) and nuclear factor kappa-B (NF-kB), and decreased inflammation in sarcoidosis-like granuloma." (PMID 36232554, 2022). "In sarcoidosis, STAT1 is primarily activated in granuloma macrophages while activated STAT3 is in T-cells and B-cells thus indicating a role for the JAK-STAT pathway in the pathogenesis of sarcoidosis." (PMID 39345281, 2024). "The majority of these SNPs were validated in AAs, with rs7549445, the top ranked SNP by p value, related to JAK1 gene, a Janus kinase, key component of the interleukin-6 (IL-6)/JAK1/STAT3 immune and inflammation response, supporting the importance of the JAK-STAT pathway in sarcoidosis." (PMID 38390497, 2023). "Analysis of tissue and circulating mononuclear cells from patients with sarcoidosis consistently revealed a constitutive JAK-STAT activation and immunohistochemistry showed constitutive activation of STAT1 in granuloma macrophages and STAT3 in surrounding lymphocytes." (PMID 39431514, 2024).
vitiligo (12 papers, 2021 to 2025). Generalized well circumscribed patches of leukoderma that are generally distributed over symmetric body locations and is due to autoimmune destruction of melanocytes. "Gramine, an antioxidant known to suppress NF‐κB and JAK/STAT3 signaling, offers dual potential in alleviating oxidative stress and immune dysregulation associated with vitiligo." (PMID 40856249, 2025). "FHB suppressed the expression of p-STAT3 in vitiligo mice in a dose-dependent manner, implying that FHB is involved in JAK-STAT pathway regulation." (PMID 37575231, 2023). "However, FHB therapy significantly hampered the increase of mRNA expression of Jak1, Jak2, Stat1, Stat2, and Stat3 in vitiligo mice, and this inhibitory effect was dose-dependent." (PMID 37575231, 2023). "In addition, network pharmacology analysis identified AKT1, RELA, and STAT3 as key targets of FHB for vitiligo treatment." (PMID 37575231, 2023). "The in vivo experiments further revealed that FHB could inhibit STAT3’s expression, phosphorylation, and dimerization to exert an anti-inflammatory and melanogenesis-promoting effect, and treat vitiligo by downregulating the JAK-STAT signaling pathway." (PMID 37575231, 2023). "According to the findings of network pharmacology and molecular docking, FHB may treat vitiligo by binding to STAT3 and decreasing its phosphorylation, hence inhibiting the transactivation of the JAK-STAT signaling pathway." (PMID 37575231, 2023). "Targeting STAT3 with miR-21-5p can decrease apoptosis in melanocytes and increase tyrosinase activity, which could be a potential treatment for vitiligo." (PMID 37731844, 2023). "In this study, we found that among lncRNAs, the expression of LOC100506314 was increased in T cells from patients with vitiligo and participated in the immunopathogenesis of vitiligo via binding to STAT3 and MIF, which could affect its downstream signaling." (PMID 37731844, 2023). "STAT3 expression was increased in patients with vitiligo and STAT3 could partly reverse the effects of miR-21-5p overexpression on melanocytes." (PMID 36187493, 2022). "To conclude, miR-21-5p may play a protective role in vitiligo via targeting STAT3." (PMID 36187493, 2022). "Based on the results of network pharmacology, molecular docking was performed to validate the binding modes of the top three active components (i.e., luteolin, quercetin, wogonin) and the top three FHB-vitiligo targets (i.e., RELA, STAT3, AKT1)." (PMID 37575231, 2023). "To further investigate the effect of FHB on the JAK-STAT pathway in vitiligo mice at the transcriptional level, we used qRT-PCR to examine the influence of FHB on the mRNA expression of Jak1, Jak2, Stat1, Stat2, and Stat3 in the lesion region." (PMID 37575231, 2023). "To verify the effect of FHB on the JAK-STAT signaling pathway in vitiligo mice in vivo, we first investigated the expression of p-STAT3, one of the markers of JAK-STAT signaling pathway activation, in vitiligo skin tissues by IHC." (PMID 37575231, 2023). "In mice with monobenzone-induced vitiligo, LBP treatment attenuated the symptoms of a vitiligo-like skin disease, inhibited infiltration of CD8+ T cells and reduced activity of the STAT3-Hsp70-CXCL9/CXCL10 signalling pathway." (PMID 36655287, 2023). "Enhanced expression of LOC100506314 suppressed STAT3, AKT, and ERK phosphorylation and nuclear protein levels of p65, which are known to participate in the pathogenesis of vitiligo." (PMID 37731844, 2023). "The results of network pharmacology and molecular docking imply that the STAT3 and the JAK-STAT pathway may be the potential therapeutic targets of FHB in vitiligo." (PMID 37575231, 2023). "Our study showed that LBP can down-regulate the ratio of p-STAT3/STAT3 in skin lesions of monobenzone-treated mice, suggesting that LBP may inhibit the activation of the STAT3-Hsp70-CXCL9/CXCL10 pathway in vitiligo treatment." (PMID 36655287, 2023).
vitiligo (continued). "Based on the findings of the “component-target-disease” network, GO and KEGG analysis, and molecular docking, we hypothesized that the STAT3 and JAK-STAT pathways may be involved in the therapeutic molecular mechanism of FHB in vitiligo." (PMID 37575231, 2023). "Nevertheless, STAT1 is not the only transducer involved in vitiligo, but STAT3 is also increased in vitiligo lesions." (PMID 34768860, 2021). "Interfering with Mfsd4a in melanocytes co-cultured with vitiligo model T cells significantly improved melanocyte activity, inhibited the levels of inflammatory cytokines TNF-α, IL-1β, and IL-6, reduced melanocyte apoptosis, and inhibited JAK/STAT3 pathway activation." (PMID 40707941, 2025). "In vitiligo, oxidative stress activates NF-κB signaling, thus inducing the expression and trans-presentation of IL-15 in keratinocytes; this enhances the activation and expression of cytotoxic proteins in CD8+ cells by activating both the STAT3 and STAT5 pathways." (PMID 39201060, 2024). "Enhanced expression of LOC100506314 inhibited the phosphorylation of STAT3, protein kinase B (AKT), and extracellular signal-regulated protein kinases (ERK), as well as the levels of nuclear protein of p65 and the expression of IL-6 and IL-17 in Jurkat cells and T cells from patients with vitiligo." (PMID 37731844, 2023).
ankylosing spondylitis (11 papers, 2010 to 2024). An autoimmune chronic inflammatory disorder characterized by inflammation in the vertebral joints of the spine and sacroiliac joints. "This study identifies chr1q32 and STAT3 as ankylosing spondylitis susceptibility loci." (PMID 21152001, 2010). "Additionally, STAT3 has been shown to promote the progression of ankylosing spondylitis (AS) through mechanisms such as interference with the Akt/mTOR signaling cascade and pyroptosis." (PMID 39188714, 2024). "STAT3 is a key signaling molecule within the Th17 lymphocyte differentiation pathway and further enhances the case for a major role of this T-lymphocyte subset in ankylosing spondylitis." (PMID 21152001, 2010). "Stat3/Arg-1 signaling was reported to play an important role in the expansion and activation of M-MDSC cells in patients with Ankylosing Spondylitis (AS)." (PMID 39013845, 2024). "As the genes IL23R, STAT3, and IL12B all influence Th17 lymphocyte differentiation/activation, this provides further evidence implicating the Th17 lymphocyte subset in the pathogenesis of ankylosing spondylitis." (PMID 21152001, 2010).
carcinoma in situ (11 papers, 2015 to 2022). "In BCs, Stat3 is implicated in the progression from carcinoma in situ to invasive BCs." (PMID 35681623, 2022). "STAT3 has been implicated in the progression from carcinoma in situ to invasive BC." (PMID 28031890, 2015). "The importance of STAT3 in transforming normal urothelium to carcinoma in situ has been elegantly shown in transgenic mouse models." (PMID 26008846, 2015). "Stat3 activation in urothelial stem cells may lead to direct progression of urothelial progenitor cells to carcinoma in situ (CIS) formation and subsequent MIBC." (PMID 29190997, 2017). "In line with these, transgenic expression of STAT3 in basal cells of mouse bladder epithelium accelerated the progression from carcinoma in situ to invasive bladder cancer under carcinogen nitrosamine treatment, compared to wild-type mice under the same treatment." (PMID 25849286, 2015). "Moreover, early expansion of primitive CK14+ expressing cells, driven by STAT3 and other pathways, leads to transition to carcinoma in situ-invasive pathway." (PMID 28031890, 2015). "We performed immunohistochemical staining of ezrin, ERK, STAT3, and AKT in tumors from patients with tongue carcinoma in situ (CIS, n = 17) and tongue squamous cell carcinoma (SCC, n = 46)." (PMID 32281236, 2020).
cognitive decline (11 papers, 2019 to 2025). "Stat3 has been associated with worsening cognitive decline in the 5xFAD mice." (PMID 35820938, 2022). "Additionally, the loss of STAT3 in reactive astrocytes and systemic treatment with a STAT3 inhibitor contribute to the restoration of cerebral network function, providing protection against spatial memory and learning impairments and improving cognitive decline." (PMID 39648181, 2024). "Deleting STAT3 or chronic treatment with a systemic STAT3 inhibitor normalized cerebral network activity, attenuated neuroinflammation and ameliorated cognitive decline of AD model mice." (PMID 35656110, 2022). "STAT3 modulates glial activation, indirectly regulates Aβ deposition, and induces cognitive decline in AD transgenic models." (PMID 33050466, 2020). "Notably, a recent study of elderly patients reported enhanced JAK/STAT3 signaling responses in CD4 + and CD8 + T cell in patients at greater risk for cognitive decline after surgery." (PMID 39953524, 2025). "Upregulation of these IEGs, along with increased BDNF protein levels following STAT3 inhibition, suggests mechanisms by which cognitive decline could be mitigated under oxidative stress and neurodegenerative conditions." (PMID 39648181, 2024). "In summary, this study demonstrated that prolonged aerobic exercise can reverse the cognitive decline caused by T2DM, which may be related to the activity of AMPK/SIRT1 and the inhibition of JAK2/STAT3 signalling in T2DM mice." (PMID 35578689, 2022). "A therapy of JAK/STAT3 pathway inhibition, mainly directed to regulate astrocytes reactivity, could be an excellent strategy to diminish neuron death and cognitive decline in AD." (PMID 33050466, 2020). "Having found that astroglial Stat3 signaling strongly modulates the inflammatory environment around plaques, Aβ burden and clearance, neurite degeneration, and network function, we next determined its effects on the severity and progression of cognitive decline." (PMID 30617153, 2019). "For example, deletion of STAT3 in astrocytes in the APP/PS1 model of AD decreased beta amyloid plaque formation and ameliorated spatial learning and cognitive decline." (PMID 32192109, 2020). "Aerobic exercise may also be used to prevent synapse formation disorders and cognitive decline through enhancing the AMPK/SIRT1 and inhibiting the JAK2/STAT3." (PMID 35578689, 2022). "Moreover, a developing of an astrocyte conditional STAT3 knockout in APP/PS1 transgenic mice leads to an anti-inflammatory profile, which could mediate Aβ clearance by microglial cells and reduce cognitive decline." (PMID 33050466, 2020).
colon adenocarcinoma (11 papers, 2012 to 2023). "In colon adenocarcinoma, p-STAT3 is an important factor associated with the extent of tumor invasion and poor prognosis." (PMID 23110625, 2012). "STAT3 is a transcription factor that has been linked with metastasis in different tumourtypes e.g. lung, colon adenocarcinoma, and PDAC." (PMID 23157946, 2012). "Pyrimethamine in colon adenocarcinoma: As commonly found in other cancers, STAT3 overactivation also constitutes a driving force in colon adenocarcinoma, and particularly so in the stem subpopulation." (PMID 35626167, 2022). "IHC analysis of p-STAT3 showed negligible staining in normal healthy tissue and strong nuclear staining in the colon adenocarcinoma specimen." (PMID 35393949, 2022). "Overall, these results demonstrate that LPA increases the proliferative potential of colon adenocarcinoma HCT-116 cells through a mechanism involving cooperation between the Rho-ROCK and STAT3 pathways involved in cell cycle control." (PMID 26418031, 2015). "Iliopoulos and coworkers also showed, in colon adenocarcinomas, a positive correlation in the expression pattern of miR-21 and STAT3 as well as a negative correlation in the expression pattern of miR-21 and PTEN." (PMID 24499937, 2014). "The PFS of patients with LGG, HNSC, SKCM, prostate adenocarcinoma (PRAD), and colon adenocarcinoma (COAD) was significantly different, and the PFS of the low STAT3 expression group was significantly higher than that of the high expression group in LGG." (PMID 37724127, 2023).
kidney cancer (11 papers, 2013 to 2026). Primary or metastatic malignant neoplasm involving the kidney. "It is shown that TGR5 suppressed STAT3 pathway by antagonizing STAT3 phosphorylation and transcriptional activity in kidney cancer cells, thereby highlighting TGR5 as a therapeutic target for treatment of kidney diseases through antagonizing STAT3 signaling." (PMID 28903349, 2017). "Currently, we noted that activation of TGR5 suppressed kidney cancer cell proliferation and migration possibly by suppressing both STAT3 and NF-κB pathways, which suggests that TGR5 is a potential kidney tumor suppressor." (PMID 28903349, 2017). "In a murine kidney cancer model (RENCA), sunitinib inhibited STAT3 activity in tumor associated MDSCs, and was found to reduce the expression of several STAT3 regulated pro-angiogenic genes." (PMID 23508517, 2013). "Additionally, it was also found that sunitinib inhibits STAT3 signaling, which is also related to the expansion of the MDSCs; consequently, in patients with kidney cancer treated with sunitinib, a decrease in MDSCs was seen as well as an improved function of T lymphocytes." (PMID 37396098, 2023). "Studies have revealed that cancer-related fibroblasts are involved in enhancing the migratory properties of the prostate, kidney, and kidney cancer, by secreting several stimulating factors such as IL-6 or CCL3 that activate STAT3." (PMID 36230984, 2022). "Together, these findings reveal a targetable enhancer mechanism that sustains HIF-2α expression and suggest that combined inhibition of JAK1/STAT3 and HIF-2α may overcome therapeutic resistance in kidney cancer." (PMID 41874563, 2026).
laryngeal squamous cell carcinoma (11 papers, 2013 to 2026). A squamous cell carcinoma that arises from the larynx. "Macrophage-derived exosomes promote PD-L1 expression in laryngeal squamous cell carcinoma through the STAT3 transcription pathway, which was further confirmed by the addition of STAT3 inhibitors." (PMID 38195554, 2024). "For example, the STAT3 decoy (double-stranded DNA containing STAT3-binding site) that sequesters dimeric STAT3 away from endogenous targets has been shown to increase apoptotic death and reduce tumor growth in laryngeal squamous cell carcinoma (PCI-37A)." (PMID 35844493, 2022). "The overexpression of STAT3 was determined in all samples of laryngeal squamous cell carcinoma." (PMID 31781300, 2019). "This activity could be mediated by ERs or GPER1 (G protein-coupled estrogen receptor 1), which was shown to trigger proliferation and migration in laryngeal squamous cell carcinoma (LaSCC) via Interleukin-6(IL-6) and signal transducer and activator of transcription 3 (STAT3)." (PMID 29498642, 2018). "Curcumin also prevented VEGF and MMP-2 production in laryngeal squamous cell carcinoma cells by reducing JAK2 and STAT3 phosphorylation and inhibiting angiogenesis." (PMID 37463912, 2023). "We, in the present study, investigated the potential involvement of PTCSC3 in laryngeal squamous cell carcinoma (LSCC) and explored its interactions with STAT3." (PMID 31171714, 2019). "This study aims to investigate the expression and function of miR-155 in laryngeal squamous cell carcinoma (LSCC), the relationship between miR-155 and its downstream target suppressor of cytokine signaling 1 (SOCS1)-STAT3 pathway, and the related clinicopathological factors." (PMID 23437123, 2013).
lipid metabolism disorders (11 papers, 2019 to 2025). "Targeting JAK-2/STAT-3 has also been reported to be beneficial for the treatment of lipid metabolism disorders." (PMID 40474319, 2025). "The reduction and inactivation of STAT3 lead to lipid metabolic disorders and promote triglyceride accumulation by upregulating the mRNA levels of ELOVL7, PPARG, MMP1, MMP13, and TIMP4, and downregulating the mRNA level of PTGS2." (PMID 39125712, 2024). "In summary, these results suggest that Thr deficiency promotes lipid synthesis, reduces lipid breakdown, and leads to lipid metabolism disorders and triglyceride deposition by downregulating STAT3 activity in primary duck hepatocytes." (PMID 39125712, 2024). "Thus, we hypothesize that COE may elevate leptin expression to activate OB-Rb, which subsequently induces increased phosphorylation of the JAK2/STAT3 pathway involved in hepatic inflammation and lipid metabolism disorder." (PMID 36539694, 2022).
Lymphadenopathy (11 papers, 2010 to 2025). Enlargement (swelling) of a lymph node. "In this context, it is worth mentioning the SOCS1 haploinsufficiency, first described in 2020, which presents with symptoms that are in part similar to those of STAT3 GOF (lymphadenopathy and autoimmune cytopenia)." (PMID 37140667, 2023). "STAT3 GOF mice also developed lymphadenopathy as they reached maturity, with a reduction in the CD8 T cell frequency but overall increased numbers of CD4, CD8, and CD19 lymphocytes (data not shown)." (PMID 36136607, 2022). "In this study, JAKi appeared effective in ameliorating STAT3-GOF symptoms, including polyarthritis, enthesitis, periodic fever, skin rash, liver dysfunction, gastrointestinal symptoms, and lymphadenopathy." (PMID 38549698, 2023). "Second, the main characteristics of STAT3 GOF are autoimmune cytopenia, lymphadenopathy, hepatosplenomegaly, autoimmune enteropathy, interstitial lung disease, autoimmune hypothyroidism, type I diabetes mellitus, and other inflammatory manifestations such as AD." (PMID 37140667, 2023).